SEMA3E (semaphorin 3E)
Diseases named in the same sentence as SEMA3E in open-access papers (continued):
Sharing a sentence is not in itself a finding about the gene and the disease.
tumor (continued). "The present analysis showed, for the first time, that the anti-tumor effect of fisetin was mediated mainly through modulation of multiple signaling pathways and via activation of CDKN1A, SEMA3E, GADD45B and GADD45A and down-regulation of TOP2A, KIF20A, CCNB2 and CCNB1 genes." (PMID 28052097, 2017). "In addition, tumor volume in the Panc28-S3EKO group was significantly lower than that of the Panc28-Ctrl group, indicating that knockout of Sema3E decreased tumor growth in vivo." (PMID 27911862, 2016). "As to Sema3E's role on tumor growth, a few studies have reported, in contrast to our findings, that Sema3E inhibits tumor growth, sometimes regardless of its effects on cancer metastasis." (PMID 27911862, 2016). "Nevertheless, no report has been published on the inhibitory effect of Sema3E on the proliferation, migration or invasion of tumor cells until now." (PMID 26036259, 2015). "Since sema3D and sema3E seemed to be the most potent inhibitors of tumor formation from U87MG cells, we extended these in-vivo studies to determine if the expression of these semaphorins would also inhibit tumor development from another GBM derived cell line." (PMID 22936999, 2012). "Sema3E expression was independent of patients' age and tumor stage, but was significantly correlated with tumor grade." (PMID 21559368, 2011). "By contrast, forced retention of Snail1 within the nucleus of Sema3E-negative tumor cells induced EMT and enhanced cell motility." (PMID 21559368, 2011). "Intravenous injection of Sema3E-negative P0 cells at no time resulted in tumor metastasis in any organ examined at 8 weeks after cell intravenous injection." (PMID 21559368, 2011). "Expression of sema3E in MDA-MB-435 cells produced a small but significant 28% decrease in the concentration of blood vessels in resulting tumors even though tumor formation from these cells was not inhibited by sema3E." (PMID 18818766, 2008). "SEMA3E is found to regulate immune cell trafficking during the development of thymocytes, and it is also found to regulate NK-cell migration and NK–DC interactions, but its role in the regulation of immune response in tumour microenvironment is not known." (PMID 32241267, 2020). "However, other reports have made contrasting observations, which are that both full-length and cleaved 61 kDa forms of Sema3E inhibited tumor angiogenesis, although they did not inhibit metastasis." (PMID 27911862, 2016). "In the case of sema3E the cleavage generates a pro-metastatic product that affects primarily endothelial cells rather than tumor cells and is thus an example for an effect that will be seen only in-vivo but will not affect in-vitro assays such as the soft-agar colony formation assay." (PMID 18818766, 2008). "In the first such example Sema3E was not able to inhibit tumor development from MDA-MB-435 cells." (PMID 18818766, 2008). "Importantly, although furin was expressed in these cell lines, the authors could not detect the p61 kDa isoform of Sema3E via immunoblot analysis, and concluded that the anti-tumor effects observed were induced by the full-length form." (PMID 27911862, 2016). "Interestingly, even though Sema3D and sema3E inhibited either proliferation or anchorage free growth of the U87MG cells in-vitro much less effectively than sema3A, they still inhibited subcutaneous tumor development as effectively as sema3A if not more effectively." (PMID 22936999, 2012).
cancer (31 papers, 2008 to 2025). A tumor composed of atypical neoplastic, often pleomorphic cells that invade other tissues. "Using a random forest algorithm, we identified SEMA3E as the most significant contributor to TCW mutations in pan-cancer analysis." (PMID 40103807, 2025). "In the case of SEMA3E, it had down-regulated expression in most of the tested cancer types, but it mainly associated with poor prognosis." (PMID 32241267, 2020). "In certain tumors, SEMA3E has been associated with progression due to distinctive signaling cascades promoting cancer cell invasiveness and metastatic spreading." (PMID 30658382, 2019). "Firstly, SEMA3E, through its receptor, PlexinD1, promotes the proliferation, migration and invasion of cancer cells through its ability to activate the oncogenic signalling of epidermal growth factor receptor (EGFR) and HER-2." (PMID 37685898, 2023). "This is not surprising, since divergent semaphorin functions in neurons and in cancer cells are commonly seen (e.g. for Sema3A, Sema3E, Sema4D, etc.), likely reflecting the involvement of different receptor complexes and signaling pathways." (PMID 37002363, 2023). "Studies have indicated that SEMA3E plays a role in the regulation of various stages of cancer development." (PMID 32582276, 2020). "SEMA3A, SEMA3D, and SEMA3E showed relatively lower level of expression averaged across all cancer types compared to the rest of the SEMA3 family members.i.e., SEMA3B, SEMA3C, SEMA3F and SEMA3G, where SEMA3F had the highest expression." (PMID 32241267, 2020). "SEMA3E and its receptor PlexinD1 are expressed in both cancer cells and diverse stromal cell populations in the TME." (PMID 30658382, 2019). "These genes related to the selected probes are mostly associated with cancer and LN metastasis, such as TP73, PDX1, FUT8, HOXD1, NMT1, and SEMA3E." (PMID 28951630, 2017). "We reported previously that in certain cancer cells Sema3E-PlexinD1 can transactivate ErbB2 signaling, promoting the invasive/metastatic phenotype." (PMID 27749937, 2016). "Sema3E has also been shown to activate this pathway in neuroblastic cells, as well as in cancer cells." (PMID 27911862, 2016). "In further experiments we confirmed the relevant role of Slug to mediate Sema3E-induced E-cadherin downregulation and increased cancer cell migration." (PMID 27749937, 2016). "Previous studies have shown that Sema3E-PlexinD1 signaling is deregulated in human cancers; however, the molecular mechanisms responsible for PlexinD1 overexpression remained undetermined." (PMID 27749937, 2016). "For instance, in endothelial cells Sema3E and its specific receptor PlexinD1 inhibit cell-substrate adhesion and exert an anti-angiogenic function, while in cancer cells they have been shown to have a pro-tumorigenic role." (PMID 27749937, 2016). "The overexpression of SEMA3C and SEMA3E in cancer cells correlates with multidrug resistance and increased metastatic capability." (PMID 26294325, 2015). "Notably, the EPDnew-validated promoter of Sema3e was found to be hypomethylated, and its human homolog has been shown to drive cancer cell invasiveness." (PMID 40950124, 2025). "Also, they have shown that overexpression of Sema3E in PC cells promoted cell proliferation and migration in vitro, while cancer cell proliferation and migration in vitro had the opposite function." (PMID 36713527, 2022). "Very interestingly, we found that SEMA3B, SEMA3D, SEMA3E, and SEMA3G genes were negatively associated with RNAss and DNAss (P < .0001), where the strongest association was observed for SEMA3G with RNAss (r = − 0.49) across cancer types." (PMID 32241267, 2020). "Moreover, knocking down either Sema3E or Plexin D1 hampered a metastatic potential of several human cancer cells upon xenotransplantation indicating the importance of these molecules in metastatic process." (PMID 30598022, 2018). "Unexpectedly, two contrasting roles of Sema3E toward cancer have been demonstrated." (PMID 30598022, 2018).
cancer (continued). "Interestingly, we observed that Sema3E was strongly expressed in the nuclei of cancer cells while its expression in normal cells was weak and mostly confined to the cytoplasm." (PMID 27911862, 2016). "The secreted semaphorin Sema3E controls cell migration and invasiveness in cancer cells." (PMID 27749937, 2016). "For our study, we found that overexpression of both full-length and cleaved Sema3E in Panc-48 cells could promote cancer cell migration and invasion, while knockout of full-length Sema3E in Panc-28 cells inhibited cell migration." (PMID 27911862, 2016). "However, cancer cells often carry an autocrine loop of proteolytically processed isoform of Sema3E (dubbed p61-Sema3E) which instead promotes cancer cell migration in PlexinD1-dependent manner." (PMID 27749937, 2016). "Moreover, the mechanisms that lead to the abnormal expression of Sema3E in cancer have yet to be addressed." (PMID 26036259, 2015). "In addition, although Sema3E in embryonic somites is known to repel Plexin-D1-expressing endothelial cells during vasculogenesis, both anti-angiogenic and pro-angiogenic effects of Sema3E have been reported in cancer cells." (PMID 21559368, 2011). "Notably, SEMA3E is a particularly intriguing gene due to its dual role in cancer biology." (PMID 40103807, 2025). "We found that SEMA3B, SEMA3D, SEMA3E, and SEMA3G were all negatively associated with cancer-stem like features, but SEMA3A, SEMA3C, and SEMA3F were positively correlated with DNAss, which indicates that SEMA3s may associate with cancer cell sensitivity or resistance to chemotherapy treatment." (PMID 32241267, 2020). "Thus far, the role of Sema3E in several cancer types has been documented." (PMID 26036259, 2015). "Sema3E, Sema4D, and Sema7A were shown to contribute to EMT, whereas Sema3B, Sema3F, and Sema5A inhibited EMT in cancer cells." (PMID 35775491, 2022). "One cluster includes SEMA3D, SEMA3E, SEMA3G and PLXNA4, which all showed primarily down-regulation in the tested cancer tumors." (PMID 32640719, 2020). "The feature selection procedure extracted several cancer-related and lymph node metastasis-related genes, such as TP73, PDX1, FUT8, HOXD1, NMT1, and SEMA3E." (PMID 28951630, 2017). "In the case of the SEMA3s, except for SEMA3E, Nrps are essential for activating the plexin receptors, and these SEMA3/Nrp/Plexin interactions frequently antagonize VEGF-induced stimulation, especially as related to angiogenesis and cancer." (PMID 22948112, 2012). "For example, genes that encode DRs such as DCC, neogenin, UNC5B, UNC5C, or TrkC are repressed in multiple cancer types, while cancer cells can also escape DR‐mediated apoptosis through autocrine overexpression of ligands including DKK1, Netrin‐1, NT‐3, Sema3E, or HGF." (PMID 34542930, 2021).
retinopathy (4 papers, 2020 to 2022). "In an oxygen-induced retinopathy model, enhanced Plexin-D1 or intravitreal Sema3E injection prevents abnormal vessel projections and leads to normal vascular remodeling." (PMID 33978913, 2022). "RORα directly binds to a specific ROR response element on the promoter of Sema3e and negatively regulates Sema3e transcription, which can impact retinopathy development via signaling through its receptor complexes located on pathological neovessels." (PMID 32098361, 2020). "In an oxygen-induced retinopathy model, intravitreal injection of Sema3E selectively suppressed extraretinal vascular outgrowth without affecting the desired regeneration of the retinal vasculature, indicating the therapeutic potential of Sema3E–Plexin-D1 signaling in retinopathy." (PMID 35045890, 2022). "In this study, we unveiled an unprecedented interplay between MSCs, neurons and myeloid cells through which MSCs inhibit aberrant NV and promote revascularization in retinopathy, at least in part, by restoring neuronal Sema3E levels and reducing pathological levels of IL-17A in myeloid cells." (PMID 33553187, 2021).
infection (2 papers, 2022 to 2023). The state of being infected such as from the introduction of a foreign agent such as serum, vaccine, antigenic substance or organism. "Similarly, it was found that Sema3E-Fc treatment reduced body weight loss in both WT and Sema3E KO mice compared to saline-Fc treated mice after Cm infection." (PMID 35983029, 2022). "In particular, Semaphorin 3E (Sema3E), a secreted semaphorin protein, is involved in cell proliferation, migration, inflammatory responses, and host defence against infections." (PMID 35983029, 2022). "Future studies are needed to delineate the role of Sema3E in the preferential development of specific DC subset and consequent promotion of the types of T cell response in infections." (PMID 35983029, 2022). "First, we injected lentivirus encoding Venus into the V-SVZ of Sema3E+/− (control) and Sema3E−/− (Sema3E-KO) mice at postnatal day 1 (P1) and analyzed the dendritic morphology of Venus+ granule cells in the GCL at 10 days post infection (dpi)." (PMID 37534039, 2023). "Interestingly, we found that the administration of exogenous Sema3E to either Sema3E KO or WT mice can modulate T cell responses, preferentially enhancing the right cytokine profile to fight against the infection." (PMID 35983029, 2022). "Moreover, we found a more significant number of IL-17+ T cells in the lungs of Sema3E-Fc treated mice than saline-Fc treated mice after Cm infection." (PMID 35983029, 2022). "Since we observed lower IL‐10 levels in the spleen and lung of Sema3E-Fc treated mice and Treg is one of the primary sources of this cytokine, we next examined CD4+ CD25+ Foxp3+ T cells in the lungs of WT and Sema3E KO mice treated with Sema3E-Fc following Cm infection." (PMID 35983029, 2022). "The results suggest that Sema3E treatment can impede Treg responses during Cm infection." (PMID 35983029, 2022). "Compared to saline-Fc treated mice, Sema3E-Fc treated WT, and Sema3E KO mice showed higher MHC‐II, CD40, CD80, and CD86 molecules on the surface of DCs following infection." (PMID 35983029, 2022).
bacterial infections (1 paper, 2022). "We recently reported that Sema3E played an important role in host defence against bacterial infection by showing that Sema3E-deficient mice exhibited more severe disease and higher bacterial growth following Chlamydia muridarum lung infection." (PMID 35983029, 2022). "More importantly, the finding that exogenous Sema3E can promote protective immunity in both Sema3E deficient and intact mice strongly suggests the potential of this protein as a target in developing novel preventive and therapeutic approaches against bacterial infections and other diseases." (PMID 35983029, 2022). "We recently reported that Sema3E is critical for host defence against bacterial infection, mainly based on a study to compare WT and Sema3E KO mice." (PMID 35983029, 2022). "In this study, we used a different approach, supplement of exogenous Sema3E, to further confirm the role of this molecule in host defence and explore the potential of Sema3E administration as prevention and therapeutic strategy for bacterial infections." (PMID 35983029, 2022). "Altogether, the study verified the importance of Sema3E in host defence against bacterial infection and suggested that a supplement of Sema3E could be a potential strategy to enhance protection against bacterial infection or vaccination." (PMID 35983029, 2022). "However, the therapeutic function of Sema3E in bacterial infection has not been investigated." (PMID 35983029, 2022).
cardiovascular diseases (1 paper, 2022). "Inactivation of Sema3E-PlexinD1 signaling has improved the recovery of cardiac function by increasing lymphangiogenesis in an adult mouse model of MI, suggesting a therapeutic possibility for targeting Sema3E-PlexinD1 signaling in cardiovascular diseases." (PMID 34735673, 2022).
inflammation (1 paper, 2023). Aberrant reaction of the microcirculation characterized by movement of fluid and leukocytes from the blood into extravascular tissues. "However, it was significantly down-regulated the expression in DXM group when compared with EB group, suggesting that Sema3E is positively correlated with airway eosinophilic inflammation, which may become a new indicator for predicting eosinophil inflammation." (PMID 38111650, 2023).
SEMA3E also shares sentences with these, for which no sentence is quoted: diabetes (3 papers); mammary adenocarcinoma (3); osteosarcoma (3); colon cancers (2); epilepsy (2); Glucose intolerance (2); liver fibrosis (2); uterine cancer (2); Alagille syndrome (1); autism (1); Axenfeld-Rieger syndrome (1); brain cancer (1); branchiootic syndrome 1 (1); carotid atherosclerosis (1); cervical intraepithelial neoplasia (1); Combined immunodeficiencies (1); gallbladder cancer (1); gangrene (1); genetic disease (1); head and neck squamous cell carcinoma (1); hepatocellular carcinoma (1); hypoglycaemia (1); hypoparathyroidism (1); hypospadias (1); idiopathic pulmonary fibrosis (1); infantile spasms (1); intellectual disability syndrome (1); iron deficiency (1); Lung (1); lung carcinoma (1).
A further 16 diseases each share a sentence with SEMA3E in 1 paper.